GDF5 (growth differentiation factor 5)
Description:
Growth factor involved in bone and cartilage formation. During cartilage development regulates differentiation of chondrogenic tissue through two pathways. Firstly, positively regulates differentiation of chondrogenic tissue through its binding of high affinity with BMPR1B and of less affinity with BMPR1A, leading to induction of SMAD1-SMAD5-SMAD8 complex phosphorylation and then SMAD protein signaling transduction. Secondly, negatively regulates chondrogenic differentiation through its interaction with NOG. Required to prevent excessive muscle loss upon denervation. This function requires SMAD4 and is mediated by phosphorylated SMAD1/5/8 (By similarity). Binds bacterial lipopolysaccharide (LPS) and mediates LPS-induced inflammatory response, including TNF secretion by monocytes.
Synonyms: BMP-14; LAP-4; BMP14; CDMP1; BDA1C; DUPANS; LAP4; OS5; SYM1B; SYNS2
Tractability: Antibody: UniProt places it where antibodies can reach, with high confidence; its Gene Ontology location is reachable by antibodies, with high confidence; UniProt predicts a signal peptide or a membrane-spanning region.
Gene: Protein-coding gene on chromosome 20 (35,433,347 to 35,454,746, reverse strand). Ensembl gene ENSG00000125965.
Subcellular location: Secreted; Cell membrane
Pathways (Reactome):
Extracellular matrix organization: Molecules associated with elastic fibres
Gene Ontology:
Molecular function: BMP binding; identical protein binding; protein binding; cytokine activity; growth factor activity; signaling receptor binding
Biological process: BMP signaling pathway; chondroblast differentiation; negative regulation of chondrocyte differentiation; negative regulation of epithelial cell proliferation; positive regulation of BMP signaling pathway; positive regulation of chondrocyte differentiation; positive regulation of SMAD protein signal transduction; cell-cell signaling; transforming growth factor beta receptor signaling pathway; cell surface receptor protein serine/threonine kinase signaling pathway; negative regulation of neuron apoptotic process; ossification involved in bone remodeling; positive regulation of neuron differentiation; regulation of transmembrane receptor protein serine/threonine kinase signaling pathway; response to mechanical stimulus
Cellular component: extracellular region; plasma membrane
Genetic constraint (gnomAD): Loss-of-function variants: 17 observed, 35.91 expected, observed/expected ratio (o/e) 0.47, 90% interval 0.32 to 0.71. The upper end of that interval is the gene's LOEUF score, 0.71, which puts it in group 2 of 6, group 1 being the genes least tolerant of losing a copy. Missense variants: 616 observed, 692.89 expected, observed/expected ratio (o/e) 0.89, 90% interval 0.83 to 0.95. Synonymous variants: 332 observed, 304.02 expected, observed/expected ratio (o/e) 1.09, 90% interval 1 to 1.2.
Homologues: Orthologues: chimpanzee GDF5 (99% identical), macaque GDF5 (98% identical), dog GDF5 (97% identical), pig GDF5 (96% identical), rabbit GDF5 (96% identical), guinea pig GDF5 (94% identical), mouse Gdf5 (91% identical), rat Gdf5 (91% identical), tropical clawed frog gdf5 (62% identical), zebrafish gdf5 (52% identical). Paralogues in human: GDF6 (41% identical), GDF7 (35% identical), BMP6 (22% identical), BMP2 (22% identical), BMP5 (22% identical), BMP10 (21% identical), BMP4 (21% identical), BMP7 (20% identical), GDF2 (20% identical), BMP3 (20% identical), GDF3 (20% identical), BMP8A (19% identical), and 19 more.
Diseases named in the same sentence as GDF5 in open-access papers:
GDF5 is named in the same sentence as 89 diseases in open-access papers, as found by Europe PMC text mining. Sharing a sentence is not in itself a finding about the gene and the disease. The quoted sentences say what the papers report.
osteoarthritis (61 papers, 2008 to 2025). A noninflammatory degenerative joint disease occurring chiefly in older persons, characterized by degeneration of the articular cartilage, hypertrophy of bone at the margins and changes in the synovial membrane. "Osteoarthritis has been associated with the presence of the T allele in rs143383, located in the promoter region of GDF5, resulting in reduced transcription." (PMID 41019141, 2025). "Specific variants of this gene, particularly GDF5 rs143384 and rs143383, have been linked to conditions such as osteoarthritis, congenital hip dislocation, and chronic pain in genome-wide association studies." (PMID 41465193, 2025). "Numerous studies have found that GDF5 mutations correlate with susceptibility to human osteoarthritis, and the TT genotype of GDF5 SNP rs143383 increases susceptibility to knee arthritis in northern Mexico." (PMID 39596516, 2024). "The GDF5 gene is a key risk locus for osteoarthritis, with GDF5-deficient mice exhibiting abnormal joint development, underscoring its critical role in joint development and homeostasis." (PMID 39596516, 2024). "Mutations in GDF5 are associated with conditions such as apical dysplasia, chondrodysplasia, synovial syndromes, syndactyly, and susceptibility to osteoarthritis." (PMID 39596594, 2024). "Special attention was given to the association between GDF5 and osteoarthritis (OA) since it represents the most common form of arthritis, which is associated with aging, and affects more than 50% of people over 65 years old, regardless of sex and ethnicity." (PMID 37895244, 2023). "It is noteworthy that a reduction in Gdf5 expression during development is linked to a risk in subsequent articular cartilage degeneration [i.e., osteoarthritis (OA)] in later life." (PMID 37492222, 2023). "GDF5 is involved in ECM anabolism and polymorphisms of GDF5 resulted in degenerative diseases such as osteoarthritis." (PMID 36777190, 2023). "Among the selected genetic variants for height, the expression of GDF5 was the most prominent and has been revealed to be involved in height and osteoarthritis." (PMID 37049604, 2023). "The GDF5 gene is a key risk locus for osteoarthritis and Gdf5-deficient mice show abnormal joint development, indicating that GDF5 is essential in joint development and homeostasis." (PMID 38123662, 2023). "CiiiDER transcription factor binding site analysis using Jaspar 2020 database revealed conserved binding sites for transcription factors linked to cartilage and/or joint development, Gdf5 regulation, and osteoarthritis (OA) pathogenesis." (PMID 37492222, 2023). "In the analysis of OA in different genders, we found that GDF5 was associated with OA in both males and females’ osteoarthritis." (PMID 37817264, 2023). "The main purpose of this article is to make a comprehensive analysis of the association between GDF5 rs143383 SNP and OA in different types of osteoarthritis, such as knee osteoarthritis, hip osteoarthritis and hand osteoarthritis." (PMID 37817264, 2023). "In particular, the SNP rs143383 (T/C) in the 5′UTR of the GDF5 gene is a major susceptibility factor for osteoarthritis in Asian and European populations." (PMID 34210342, 2021). "Polymorphisms in GDF5 are also studied in association with various types of skeletal dysplasia (e.g., chondrodysplasia or brachydactyly) and osteoarthritis, which is frequently preceded by untreated DDH." (PMID 34203285, 2021). "Although few reports have investigated the association between the GDF5 gene and orthopedic CPSP, GDF5 gene expression and polymorphic markers affecting osteoarthritis pain, particularly joint pain, have been published in humans from different ethnic groups." (PMID 34210342, 2021). "The expression and function of GDF‐5 are highly associated with the pathogenesis of osteoarthritis (OA)." (PMID 33522652, 2021). "The GDF5 gene has been repeatedly reported to be associated with osteoarthritis through genetic studies." (PMID 31482140, 2019).
osteoarthritis (continued). "Eight DXA area loci associate with osteoarthritis, including rs143384 in GDF5 and a missense variant in COL11A1 (rs3753841)." (PMID 31053729, 2019). "We identified two loci that reached genome-wide significance in the UK Biobank: rs143384, located in GDF5 (P = 1.32 × 10−12), a gene previously implicated in osteoarthritis; and rs2808772, located near COL27A1 (P = 1.49 × 10−8)." (PMID 31482140, 2019). "Significant increase in the frequency of risk allele (T) of GDF-5 in cases of osteoarthritis is consistent with previous report demonstrating association of polymorphism in GDF-5 with OA." (PMID 29129999, 2017). "A genetic deficit mediated by SNP rs143383 that leads to reduced expression of GDF5 is strongly associated with large-joint osteoarthritis." (PMID 24466161, 2014). "As the role of GDF5 in skeletogenesis is well established, GDF5 was examined in a candidate gene analysis aiming to identify genes that harbour osteoarthritis (OA) susceptibility alleles in Japanese and Han Chinese populations." (PMID 24466161, 2014). "A single nucleotide polymorphism in the GDF5 gene has been reported to be related to susceptibility to osteoarthritis." (PMID 23356643, 2013). "GWAS also identified a SNP in the GDF5 gene which is strongly associated both with low adult height and susceptibility to osteoarthritis (OA)." (PMID 23705017, 2013). "A single nucleotide polymorphism in the human GDF5 promoter that reduces its transcriptional activity is associated with susceptibility to osteoarthritis." (PMID 23356643, 2013). "The allele A of the SNP rs143383 in the 5′ promoter region of the GDF5 gene was found to be associated with an increased risk of osteoarthritis, and shows decreased transcriptional activity of GDF5 in chondrogenic cells." (PMID 22905146, 2012). "Strong evidence indicates that the derived allele of SNP rs143383 is associated with an increased risk of osteoarthritis, which is associated with decreased transcriptional activity of the GDF5 gene in chondrogenic cells." (PMID 22905146, 2012). "A common functional SNP in the 5′ UTR of GDF5 (+104T/C; rs143383) has been associated with osteoarthritis (OA), the commonest form of human arthritis characterized by degeneration of articular cartilage and bone remodelling." (PMID 19343178, 2009). "Proteomic analysis was validated by detecting differentially expressed genes such as GDF5, that have been identified as osteoarthritis susceptibility genes by gene association studies." (PMID 19011694, 2008). "A functional single nucleotide polymorphism (SNP) in the 5'-untranslated region of GDF5 (rs143383) was reported to be associated with osteoarthritis susceptibility." (PMID 18947434, 2008). "Recently, a functional single nucleotide polymorphism (SNP) in the 5'-untranslated region of GDF5 (rs143383; +104T/C) was found to be significantly associated with osteoarthritis in people of Japanese and Han Chinese origin." (PMID 18947434, 2008). "Geometric parameters of the hip are known to be associated with osteoarthritis, and developmental dysplasia of the hip often leads to osteoarthritis, with research showing shared genetic risk factors between the two conditions, including associations with GDF5 and COL11A17,8." (PMID 40205036, 2025). "The GDF5 rs143384 polymorphism is one of the most widely studied in relation to osteoarthritis." (PMID 41465193, 2025). "The GDF5 gene, which encodes growth differentiation factor 5, contains a functional single nucleotide polymorphism (SNP), rs143383, that has been consistently associated with osteoarthritis development." (PMID 40647646, 2025). "In humans, mutations in the GDF5 gene are linked to a spectrum of clinical features such as short stature, shortened digits, joint dislocations or fusions, and hip- and knee-joint dysplasia, often accompanied by osteoarthritis." (PMID 38392197, 2024).
osteoarthritis (continued). "Functional studies revealed that the presence of T alleles at these SNPs leads to reduced expression of reporter genes in cultured articular cells and is associated with lower GDF5 transcript levels in the articular cartilage of individuals with osteoarthritis." (PMID 38392197, 2024). "In mice, Gdf5-null mutations result in a range of phenotypic abnormalities, including shorter feet and limbs, the absence of joints in digits, wrists, and ankles, altered tendon structures, missing knee ligaments, and a heightened risk of osteoarthritis." (PMID 38392197, 2024). "Furthermore, we also analyzed the osteoarthritis of different genders and found that the GDF5 rs143383 SNP was associated with both men and women and was still significant in the Caucasian population." (PMID 37817264, 2023). "In addition, genome-wide association studies (GWASs) have suggested that GDF5 gene polymorphisms are associated with knee and hip arthrosis." (PMID 37895244, 2023). "It is reasonable to believe that rs143384 may affect GDF5 gene expression and is associated with osteoarthritis and orthopedic CPSP." (PMID 34210342, 2021). "The growth and differentiation factor 5 (GDF‐5) is known to play a key role in cartilage morphogenesis and homeostasis, and a single‐nucleotide polymorphism in its promoter sequence was found to be associated with osteoarthritis (OA)." (PMID 32497388, 2020). "Meta-analysis has also reported significant association of GDF-5 polymorphism with osteoarthritis." (PMID 29129999, 2017). "Additionally, a functional polymorphism site of GDF5 is associated with susceptibility to osteoarthritis." (PMID 25072641, 2014). "GDF5 is a susceptibility gene for osteoarthritis (OA) and mutations in GDF5 are associated with a wide variety of skeletal malformations ranging from complex syndromes such as acromesomelic chondrodysplasias to isolated forms of brachydactylies or multiple synostoses syndrome 2 (SYNS2)." (PMID 24098149, 2013). "The factors that we have identified could serve as novel therapeutic targets, with their depletion restoring the expression levels of GDF5 in patients with the osteoarthritis susceptibility T allele." (PMID 23825960, 2013). "An additional study of a gene associated with osteoarthritis (GDF5) discovered that a promoter polymorphism which created a small reduction of the expression of the T allele (less than 27%), significantly increased individuals susceptibility to developing osteoarthritis." (PMID 21345208, 2011). "Furthermore, the association between osteoarthritis and GDF5 is more clear than previous studies." (PMID 32928309, 2020). "This may be a cause or a consequence of the osteoarthritis disease process and will need to be surmounted if treatment with exogenous GDF5 is to be advanced as a potential means to overcome the genetic deficit conferring osteoarthritis susceptibility at this gene." (PMID 24466161, 2014). "Genes associated with DDH and osteoarthritis include FRZB, CX3CR1, ASPN, DKK1, PDRG1, GDF5, UQCC1, and TGF-β1." (PMID 41019141, 2025). "Intra-articular treatment with recombinant human GDF5 prevented disease progression and stimulated cartilage repair in a medial meniscal transection model of osteoarthritis in rats." (PMID 37256145, 2023). "Dysregulation of Gdf5 results in joint dysmorphogenesis often leading to progressive joint degeneration or osteoarthritis (OA)." (PMID 37492222, 2023). "CHST3, SMAD3, and GDF5 accrued the highest levels of confidence, each with 6 different lines of evidence in support of their involvement in osteoarthritis." (PMID 34450027, 2021). "Numerous studies have focused on the effect of gene polymorphisms on complex diseases in recent years and have shown that the GDF5 gene contributes to various osteoarthritis forms." (PMID 34210342, 2021). "It is reported that miR-21 promoted the chondrogenesis of osteoarthritis by directly targeting GDF5." (PMID 32508644, 2020).
osteoarthritis (continued). "In the first reported GWAS of knee pain using the UK Biobank resource, we identified variants in or near GDF5 and COL27A1, which were subsequently supported in osteoarthritis cohorts from the 23andMe, OAI and JoCo cohorts." (PMID 31482140, 2019). "Several studies have assessed the association between GDF5 rs143383 polymorphism and the susceptibility of musculoskeletal degenerative diseases, such as intervertebral disc degeneration (IDD) and osteoarthritis (OA), but the results are inconsistent." (PMID 30217184, 2018). "Given GDF5 involvement in hip development, and osteoarthritis (OA) and developmental hip dysplasia (DDH) risk, here we sought to assess the role(s) of GDF5 and its regulatory sequence on the development of hip morphology linked to injury risk." (PMID 30388100, 2018). "Growth differentiation factor 5 (GDF5), a known BMP, is expressed in cartilage and regulates chondrogenesis, and mutations have been shown to cause osteoarthritis." (PMID 27030100, 2016). "The implication of GDF5 in chondrogenesis and joint formation can finally be highlighted in connection with osteoarthritis (OA; MIM #165720), the most common form of late-onset destruction of articular cartilage in synovial joints nowadays." (PMID 24098149, 2013). "This work implicates SOX11 as a potential regulator of GDF5 expression in joint maintenance and suggests a possible role in the pathogenesis of osteoarthritis." (PMID 23356643, 2013). "The growth differentiation factor 5, coded by GDF5, is a cartilage anabolic protein and has been linked with both osteoarthritis and disc degeneration." (PMID 23185509, 2012). "Patients with osteoarthritis have upregulated GDF5 in cartilage relative to healthy controls." (PMID 41019141, 2025). "Its function is still unknown in COPD, but administration of GDF5 could promote cartilage repair by inhibition of inflammation in osteoarthritis models." (PMID 37886639, 2023). "In addition, patients with NPS often develop degenerative arthritis further linking the regulation of Gdf5 to OA." (PMID 37492222, 2023). "Decreased GDF5 expression in cartilage could lead to chronic arthritis in TNF-transgenic mice, whereas inflammatory conditions might influence GDF5 expression via fibroblasts (inflammatory infiltration indicator) in osteoarthritis." (PMID 34210342, 2021). "Enlightened by previous reports for the functional SNPs (rs143383 & rs143384) of GDF5 in osteoarthritis, we carried out a replication study in Chinese population with 218 patients and 360 controls and achieved a significant signal (p= 0.02 for rs143384 and p=0.007 for rs143383)." (PMID 31660079, 2019). "Overall, there is sufficient and solid biological evidence relating the GDF5 gene with knee osteoarthritis, and we assume that this finding is due to detection of knee pain caused by osteoarthritis, rather than other pathologies." (PMID 31482140, 2019). "Previous studies demonstrated that GDF5 was a protective factor in osteoarthritis development and exogenous GDF5 could alleviate OA progression." (PMID 31660079, 2019). "Genetic factors including the level of expression of the fingerprint of genes involved in the development of bones and cartilage such as GDF-5 or ESR-α or CALM-1 are known to be strong determinants of the osteoarthritis (OA) in Caucasian and Oriental populations." (PMID 29129999, 2017). "Polymorphisms and mutations in several genes, such as transforming growth factor β (TGF-β), bone morphogenetic protein (BMP), growth differentiation factor 5 (GDF5), secreted frizzled-related protein 3 (FRZB), and matrilin-3 (MATN3) predisposes individuals to early-onset osteoarthritis." (PMID 27104523, 2016). "We speculated that this deficit could be attenuated by the application of exogenous GDF5 protein and as a first step we have assessed what effect such application has on primary osteoarthritis chondrocyte gene expression." (PMID 24466161, 2014).